PHACTR2 (phosphatase and actin regulator 2)
Synonyms: C6orf56; KIAA0680
Tractability: Antibody: its Gene Ontology location is reachable by antibodies, with high confidence; the Human Protein Atlas places it where antibodies can reach. PROTAC: ubiquitination databases record sites on it; its protein half-life has been measured.
Gene: Protein-coding gene on chromosome 6 (143,536,845 to 143,831,185, forward strand). Ensembl gene ENSG00000112419.
Subcellular location: Membrane (Isoform 2); Membrane (Isoform 4)
Subcellular location (Human Protein Atlas): Golgi apparatus; Plasma membrane
Pathways (Reactome):
Hemostasis: Platelet degranulation
Gene Ontology:
Molecular function: protein binding; actin binding
Biological process: actin cytoskeleton organization
Cellular component: plasma membrane; platelet alpha granule membrane; membrane
Genetic constraint (gnomAD): Loss-of-function variants: 19 observed, 46.54 expected, observed/expected ratio (o/e) 0.41, 90% interval 0.28 to 0.6. The upper end of that interval is the gene's LOEUF score, 0.6, which puts it in group 2 of 6, group 1 being the genes least tolerant of losing a copy. Missense variants: 558 observed, 621.49 expected, observed/expected ratio (o/e) 0.9, 90% interval 0.84 to 0.96. Synonymous variants: 220 observed, 243.75 expected, observed/expected ratio (o/e) 0.9, 90% interval 0.81 to 1.01.
Homologues: Orthologues: chimpanzee PHACTR2 (98% identical), macaque PHACTR2 (95% identical), rabbit PHACTR2 (90% identical), pig PHACTR2 (90% identical), dog PHACTR2 (87% identical), guinea pig PHACTR2 (85% identical), mouse Phactr2 (80% identical), rat Phactr2 (79% identical), tropical clawed frog phactr2 (54% identical), zebrafish phactr2 (37% identical), Drosophila melanogaster CG32264 (30% identical), Caenorhabditis elegans phac-1 (23% identical). Paralogues in human: PHACTR4 (38% identical), PHACTR1 (32% identical), PHACTR3 (28% identical).
Diseases named in the same sentence as PHACTR2 in open-access papers:
PHACTR2 is named in the same sentence as 22 diseases in open-access papers, as found by Europe PMC text mining. Sharing a sentence is not in itself a finding about the gene and the disease. The quoted sentences say what the papers report.
Parkinson disease (3 papers, 2010 to 2022). A progressive degenerative disorder of the central nervous system characterized by loss of dopamine producing neurons in the substantia nigra and the presence of Lewy bodies in the substantia nigra and locus coeruleus. "The genes in one region are known to be involved in imprinting in human and mouse placenta (region Ger1 - Zac/Plagl1) and include a further gene suspected to be a risk factor in Parkinson's disease (Phactr2)." (PMID 22956910, 2012). "PHACTR2 is involved in phosphate and actin regulation and has been implicated in Parkinson's disease." (PMID 20546594, 2010). "Its activity is implicated in Parkinson’s disease, Alzheimer’s disease and multiple sclerosis, and some evidence exists that PHACTR2 may influence the development of cancer." (PMID 36430972, 2022).
breast carcinoma (2 papers, 2020 to 2022). "A decrease in the transcription levels of human invasion signature (HIS) genes (ARHGDIB, CAPZA2, PHACTR2, CDC42, XRCC5, and CAV1) has been also demonstrated by real-time PCR, with high expression of these genes being a hallmark of actively metastasizing breast cancer cells." (PMID 36143471, 2022). "We have shown that OCT-1 knockdown suppresses the expression of the ARHGDIB, CAPZA2, PHACTR2, CDC42, XRCC5, and CAV1 genes, which is known to be increased in actively metastasizing breast cancer cells." (PMID 36143471, 2022).
multiple sclerosis (2 papers, 2022). A progressive autoimmune disorder affecting the central nervous system resulting in demyelination. "A further four—ATP9A, TMEM232, PHACTR2 and SLC6A11—out of the seven autoimmune genes identified in this study can also be linked to multiple sclerosis development." (PMID 36517845, 2022).
esophageal squamous cell carcinoma (1 paper, 2022). Esophageal squamous cell carcinoma (ESCC) is a type of esophageal carcinoma (EC) that can affect any part of the esophagus, but is usually located in the upper or middle third. "PHACTR2 (Phosphatase and Actin Regulator 2) is significantly associated with lung adenocarcinoma and is one of the hub genes involved in esophageal squamous cell carcinoma." (PMID 36143471, 2022).
inflammatory bowel disease (1 paper, 2023). A spectrum of small and large bowel inflammatory diseases of unknown etiology. "Another CpG site contributing to the separation of patients and controls was cg18925478 within the PHACTR2 gene encoding for the phosphatase and actin regulator 2 that has previously been linked with the development of inflammatory bowel disease." (PMID 37662940, 2023).
liver fibrosis (1 paper, 2023). "This led to the identification of several cis-eQTLs, including those for phosphatase and actin regulator 2 (Phactr2) and eukaryotic translation initiation factor 3 subunit H (Eif3h), the gene expression of which significantly correlated with liver fibrosis." (PMID 37000167, 2023).
Obesity (1 paper, 2025). Accumulation of substantial excess body fat. "Proteomic profiling quantified identified 135 differentially expressed proteins (57 upregulated, 78 downregulated), with PHACTR2 and PLIN2 upregulated in obesity and ADAR down-regulated in obesity." (PMID 40822952, 2025).
systemic lupus erythematosus (1 paper, 2023). An autoimmune multi-organ disease typically associated with vasculopathy and autoantibody production. "Furthermore, the PHACTR2 protein was suggested as a potential marker of disease exacerbation in systemic lupus erythematosus (SLE)." (PMID 37662940, 2023).
genetic diseases (1 paper, 2023). "Thus, PHACTR2 may join other regulators of actin dynamics that have been demonstrated to cause human genetic diseases." (PMID 36674904, 2023).
PHACTR2 also shares sentences with these, for which no sentence is quoted: tumor (3 papers); cancer (2); Alzheimer disease (1); asthma (1); autoimmune disease (1); breast tumor (1); cardiomyopathy (1); Dilated (1); endometriosis (1); hematologic malignancies (1); lung adenocarcinoma (1); non-small cell lung carcinoma (1); psoriasis (1).